BAP1 (BRCA1 associated deubiquitinase 1)
Diseases named in the same sentence as BAP1 in open-access papers (continued):
Sharing a sentence is not in itself a finding about the gene and the disease.
tumor (continued). "The BAP-1 gene is located on chromosome 3p21.1 and is involved in epigenetic modulation of chromatin, DNA- and cell repair as well as tumor growth suppression." (PMID 39201396, 2024). "BAP1 analyses were performed on formalin-fixed, paraffin-embedded tumor tissue samples of the patients, while WT1 and calretinin information were obtained from the histopathological diagnosis records." (PMID 38280040, 2024). "The identification of early mutations in genes such as GNAQ/11, BAP1 and CYSLTR2, among others, and the understanding of their roles in tumor growth and metastasis, have greatly enhanced our understanding of UM and provided potential targets for therapy." (PMID 38920653, 2024). "Secondary to VHL, additional mutations (most notably in PBRM1, BAP1, and SETD2) enlist a large number of genetic and epigenetic events to drive advanced tumor evolution." (PMID 38618956, 2024). "Molecular profiling of the tumor was performed for 22 of 34 patients, of which 18 patients had a BAP1-negative tumor and 4 patients had a BAP1-positive tumor." (PMID 38319670, 2024). "In conclusion, this study identifies a novel mechanism by which BAP1 can regulate glycolysis in tumor cells." (PMID 39587076, 2024). "To gain insight in the molecular consequences of EZH2 inhibition and the increased sensitivity to the combination in BAP1 depleted cells, we performed RNA sequencing (RNA-seq) on primary tumor cell lines treated with EZH2 inhibitor." (PMID 38054839, 2024). "These tumours have alterations in chromosomal numbers and are associated with mutations in MET, CDKN2A, SETD2, BAP1, PBRM1, NFE2L2, and mTOR genes and have a better prognosis when compared with clear cell RCC in the organ-confined stage." (PMID 38265103, 2024). "We used curated survival data from the TCGA Clinical Data Resource to perform tumor-specific survival analyses stratified by BAP1 activity class and noted improved progression-free survival outcomes for wildtype-like UVM and KIRC tumors." (PMID 39554490, 2024). "BAP1 promotes the development and recruitment of T cells and is essential to maintain the anti-tumor immunogenicity." (PMID 39587076, 2024). "Studies have shown that the anti-tumor effect of BAP1 is partly due to the ubiquitination of H2A on the promoter of SLC7A11, thus inhibiting the expression of SLC7A11 and inducing ferroptosis." (PMID 38475936, 2024). "Correct interpretation of pathogenicity can improve prognosis of the patients through tumor screening with better understanding of BAP1-TPDS." (PMID 37956408, 2024). "When BAP-1 is functioning correctly, it acts as a crucial guardian against tumor development in ccRCC by inhibiting cell proliferation and aiding in DNA repair." (PMID 39796121, 2024). "Our findings suggest that diminished BAP1 levels promote a tumor phenotype primarily under conditions of genotoxic stress (involving gene–environment interactions)." (PMID 39201746, 2024). "The PARP inhibitor niraparib was investigated in a phase II trial (NCT03207347, UF-STO-ETI-001) involving patients with BAP1 and other DDR-deficient neoplasms." (PMID 38730642, 2024).
tumor (continued). "Another marker that has been reported to help predict prognosis and to individualize treatment is BAP-1, a tumor suppressor involved in homologous recombination-mediated DNA repair and cell death." (PMID 39685780, 2024). "The tumor-suppressor activity of BAP1 is mediated, in part, by the repression of SLC7A11 expression through deubiquitinating of H2A on the SLC7A11 promote." (PMID 38267442, 2024). "Surprisingly, contrary to previous research on tumor, most cancer types showed a positive correlation with BAP1 expression." (PMID 39034372, 2024). "In particular, wild type BAP1 was located in the nucleus (required for the tumor suppressor activity), whereas mutant BAP1 proteins showed impaired nuclear localization and an increased cytoplasmic appearance." (PMID 38175637, 2024). "Over the years, BAP1 has been found to act independently as a tumor suppressor through its de-ubiquinating activity, which regulates target genes involved in transcription, cell cycle control, DNA damage repair, apoptosis, and cell metabolism." (PMID 38903495, 2024). "BAP1 has been proposed to play a critical role in controlling tumor plasticity and normal cell fate." (PMID 38045292, 2024). "Oncogenes (e.g., NOTCH1 and ERBB2) tended to increase in centrality in tumor modules while tumor suppressors (e.g., BAP1, AKT1, and EP300) decreased in centrality." (PMID 38685127, 2024). "The panel NGS of the primary tumor revealed pathogenic mutations in VHL, BAP1 and NF2 and likely pathogenic mutations in KDM6A, as well as ABL." (PMID 38611655, 2024). "Bap1 knockout resulted in a notably decrease in the tumor infiltration of CD45+CD8+ T cells and CD45+CD4+ T cells, while increased the infiltration of repressive CD11b + Gr1 + myeloid cells." (PMID 39350280, 2024). "We identified a relationship between BAP1 driver mutations and the epigenetic upregulation of EMT genes (IL20RB and WT1), correlating with increased tumour immune infiltration, advanced stage, and poorer patient survival." (PMID 39592856, 2024). "The increased accuracy of tumor delineations resulted in the moderate performance achieved in classifying BAP1+ from BAP1− patients." (PMID 39669009, 2024). "BAP1 is also a highly important tumor suppressor, expressed and functional across many cell types and tissues." (PMID 38529289, 2024). "To explore the role of gene–environment interactions in MMs from Bap1-mutant mice, we investigated proinflammatory and protumorigenic factors and the tumor immune microenvironment (TIME)." (PMID 38592450, 2024). "We also detected BAP1 variants in both regions in four tumours each with a VAF consistent with their presence in most or all tumour cells (82–100%) and concomitant deletion of the other BAP1 allele." (PMID 39766052, 2024). "These combined approaches enabled the identification of six tumour suppressor driver genes—namely BAP1, CREBBP, FAT1, NCOA6, RAD21 and UBR5—as regulators of the DDR and maintenance of chromosomal stability in NSCLC." (PMID 39738653, 2024). "BAP1 is mainly localized in the nucleus and exerts tumor suppressive effects by binding to the RING finger domain of BRCA1." (PMID 39587076, 2024). "Alterations in tumor-suppressor gene function, in particular BAP1 located on chromosome 3, have been shown to correlate with increased risk of tumor metastasis." (PMID 38473430, 2024). "According to the waterfall plot, BAP1, a tumor suppressor gene located on 3p21.1, often alters in patients with chromosome three copy number loss, resulting in homozygous BAP1 mutations." (PMID 38333293, 2024).
tumor (continued). "Although thoracoscopic pleural biopsies that reveal tumor involvement of fat aid pathologists in making a diagnosis, utilizing BAP1/MTAP/CDKTA tests can potentially confirm the diagnosis, even without evident invasion." (PMID 38730667, 2024). "Higher MTNR1A RNA levels were observed in patients with a BRCA1 Associated Protein 1 (BAP1) mutation, and higher NQO2 RNA levels were noted in patients with the epithelioid tumor cell type." (PMID 39201396, 2024). "Germline genetic screening should be performed in the context of tumours belonging to the BAP1 spectrum with additional supportive information (e.g., IHC BAP1loss, age of onset, and personal or family history of cancer)." (PMID 38673021, 2024). "Nonetheless, the mechanisms that account for the tumor suppressor function of BAP1 have only begun to be elucidated." (PMID 37009801, 2023). "In models of MPM overexpressing EZH2 due to BRCA-1-associated protein 1 (BAP1) loss, pharmacological EZH2 inhibition showed significant anti-tumor activity." (PMID 36900330, 2023). "A possible explanation for this phenomenon is that the tumor immune microenvironment in BAP1 muted gene is more inflammatory." (PMID 36776840, 2023). "In contrast to the UM samples with WT BAP1, macrophages, CD4+ T lymphocytes, CD8+ T lymphocytes, tumor-associated fibroblasts, and mast cells had higher infiltration in the UM samples with MUT BAP1." (PMID 37710185, 2023). "The deubiquitinase BAP1 is multifunctional protein with tumor suppressor activity involved in chromatin remodeling, DNA damage response, cell cycle regulation, cell death, and differentiation." (PMID 35920959, 2023). "In our study, we analyzed the FoxP3 transcriptome across TCGA cancers, and we found that the FoxP3 was highly expressed in the tumor tissues of ccRCC patients with BAP1- or SETD2-mutant genotype." (PMID 37569676, 2023). "A mutation of the BRCA1-associated protein-1 (BAP1), as a tumor-suppressor gene placed on chromosome 3, has been detected in 47% of patients with primary UM." (PMID 36900228, 2023). "This revealed concordance between our mutant organoids and primary tumor tissues, which highlighted the enrichment of the ductal/progenitor signature only in BAP1-FLC tumors." (PMID 37137901, 2023). "BAP1 is identified to inhibit tumor proliferation by stabilizing LATS, while tripartite motif-containing 29 (TRIM29) directly binds to YAP1 and avoids YAP1 from ubiquitinated degradation." (PMID 38174069, 2023). "For example, the oncogenic circRNA has-circ-0052112 enhances tumor cell invasion and migration by sponging miR-125a-5p, a tumor suppressor that inhibits the BAP1 oncogene." (PMID 38125536, 2023). "To date, European recommendations for BAP1 carriers have not been published but are necessary due to the emerging phenotype of this recently described syndrome and increased identification of BAP1 carriers via large gene panels or tumour sequencing." (PMID 37607989, 2023). "We identified a potential CES3 enhancer peak located ~5 kb upstream of the CES3 transcriptional start site (TSS), displaying consistently lower accessibility in tumor cells of all BAP1 mutants as compared with other tumors and PT cells from NATs." (PMID 36973268, 2023). "Despite these complexities, genetically engineered mouse models (GEMM) provide fundamental evidence that BAP1 is tumor suppressor." (PMID 36669126, 2023). "In total, 0.2% of the analyzed cells had small, round nuclei with high BAP-1 expression, likely representing a population of tumor-infiltrating lymphocytes." (PMID 37117276, 2023). "In the present study, we used sequential testing of tumor and blood DNA from UM patients for differential diagnosis of BAP1-TPDS." (PMID 35920959, 2023). "In two-step clustering of primary tumor melanocytes, the highest silhouette measure of cohesion and separation was obtained with nucleus area, nucleus circularity, nBAP-1 OD, and cytoplasm BAP-1 OD (0.38)." (PMID 37117276, 2023).
tumor (continued). "The tumor growth patterns in later stage are consistent with that in early stage and depletion of BAP1 in BE2C cells markedly retarded tumor growth and overexpression of MYCN in shBAP1 cells dramatically increased the tumor growth." (PMID 37543638, 2023). "Using our strategy, which requires initial sequencing of tumor DNA, only half as much VUS are expected due to loss of one BAP1 allele in most tumors." (PMID 35920959, 2023). "We propose that BAP1 exerts two-level protection against cancer development through its roles in genome stability and apoptosis, the two critical steps that can lead to neoplasia when defective." (PMID 37009801, 2023). "Although it was well known that the role of BAP1 as a tumor suppressor or oncogene is cellular and tissue context or cancer-type dependent, this is the first time to find that knockdown and overexpression of same gene in one tumor type have same phenotype." (PMID 37543638, 2023). "In the positive ion mode, F1-scores were 0.65, 0.35, and 0.64 for patients harboring a BAP1, SF3B1, and EIF1AX-mutated tumor, respectively." (PMID 36982149, 2023). "Loss of VHL is often associated with loss of other tumor suppressor genes including PBRM1, BAP1 and SETD2, which are also located on chromosome 3p." (PMID 37173966, 2023). "It was recently reported that BAP1 is involved in the cellular calcium release, which functions as a tumor suppressor in the cytoplasm." (PMID 37272766, 2023). "BAP1 tumor suppressor activity thus appears to be significantly influenced by the management of epithelial identity." (PMID 37547759, 2023). "Inactivation of BAP1 in tumor cells results in increased expression of SLC7A11, leading to enhanced cystine uptake, GSH synthesis, and resistance to ferroptosis." (PMID 37552314, 2023). "BAP1- or PTEN-mutated ccRCCs showed significantly higher CD8 + TIL counts at the invasive margin and at the tumor periphery in comparison to other ccRCCs (p = 0.03)." (PMID 36562826, 2023). "Accordingly, a gene signature using all differentially expressed genes identified in the mutant organoid models, was able to clearly separate the primary FLC tumor samples into 3 clusters: the BAP1-FLC tumors, the fusion-FLC tumors and the normal livers." (PMID 37137901, 2023). "While many BAP1 activities are likely involved in tumor suppression, two important mechanisms have recently drawn considerable attention: genome stability and apoptosis." (PMID 37009801, 2023). "Recent studies have shown that BAP1 acts as a tumor suppressor in ICC by modulating ERK1/2 and JNK/c-Jun pathways." (PMID 36646721, 2023). "BAP1 and LRP1B mutations were found in the MPM693 tumor and corresponding patient-derived cell line." (PMID 37345150, 2023). "We looked for enriched pathways in these clusters by gene ontology analysis and compared these with gene ontologies found by analysis of datasets on both fusion-FLC and BAP1-FLC tumor tissues." (PMID 37137901, 2023). "Reassuringly, these same tumor samples also correlated highly to normal liver, suggesting a certain transcriptomic heterogeneity within these BAP1-FLC tumors." (PMID 37137901, 2023). "The tumour suppressor BAP1 enhances ferroptosis by regulating the expression of cystine transporter SLC7A11, thus improving the control of tumour growth." (PMID 36600313, 2023). "Already in 2013, the genome of the clear cell RCC was identified, which is characterized by the absence or mutation of the VHL tumour suppressor gene (localized at 3p25) and frequent inactivation of the chromatin-modifying genes PBRM1, BAP1 and SETD2." (PMID 36672289, 2023). "To further explore the oncogenic function of BAP1 in NB, we performed a serial of in vitro cellular and in vivo tumor xenograft assays using the BAP1 overexpressed BE2C cells." (PMID 37543638, 2023).
tumor (continued). "Although we previously showed that a dark eye color was associated with tumor pigmentation, we now show that the tumor’s genetic status (chromosome 3 and 8q/BAP1 status) is also related to tumor pigmentation." (PMID 37193315, 2023). "Mutations of BAP1 abolish the ability of cancer cells to promote ferroptosis highlighting the role of epigenetic regulation of ferroptosis in BAP1-mediated tumor suppressive functions." (PMID 36338517, 2022). "Both neoplasms showed a loss of E-cadherin and conserved expression of KDM6A; BAP1 showed a heterogeneous staining pattern in the first tumor and conserved expression in the second neoplasm." (PMID 35359182, 2022). "Tumors with alterations in only BAP1 showed a distinct pattern of expression of inflammatory tumor microenvironment genes, including activation of interferon signaling and IRF TFs and high LAG3 and VISTA expression." (PMID 36428720, 2022). "These include methylation patterns, copy number alterations, and mutually exclusive driver mutations affecting oncogenes, including BAP1, CDKN2A/B, and the TERT promoter, which are associated with particularly aggressive tumor biology." (PMID 35299730, 2022). "Moreover, BAP1 deficiency drives the reprogramming of cell metabolism, promoting anaerobic glycolysis for energy production rather than mitochondrial respiration and increasing extracellular lactate secretion which induces immune evasion, tumour growth and cell malignant transformation." (PMID 36318367, 2022). "That is, VHL mutation acts as an initiative event to induce tumor occurrence, while PBRM1, BAP1 and SETD2 cause DNA repair defect and cell overgrowth." (PMID 35918352, 2022). "Currently, BAP1 genetic testing is recommended for patients who develop two or more tumors of the BAP1-TPDS spectrum or for those affected by only one of those tumors provided they have a first- or second-degree relative with a confirmed BAP1-TPDS tumor." (PMID 35885614, 2022). "BAP1 is a tumor-suppressor gene located on chromosome 3 (3p21.1), which encodes for a nuclear deubiquitinase involved in cell growth and cancer pathogenesis." (PMID 35480119, 2022). "Significant focal copy number changes as identified by GISTIC analysis (q-value of < 0.001) occurred on chromosomes 3, 9, 16 and 22 in regions that contain tumour suppressor genes, BAP1 (chr3), CDKN2A (chr9) and NF2 (chr22)." (PMID 35637530, 2022). "BAP1 tumor suppressor activity has been attributed to its nuclear localization, where it helps to maintain genome integrity." (PMID 34976173, 2022). "We report here the results of our genetic screening of both germline and tumor samples from a cohort of BAP1-TPDS patients, identifying six different germline BAP1 PVs in seven families." (PMID 35885614, 2022). "Several studies have highlighted that BAP1 tumour suppressor activity is strictly cell type- and context-dependent: inactivation of BAP1 or catalytically inactive mutants (i.e. C91A) can drive opposite phenotypes in different tissues." (PMID 36318367, 2022). "In this article we provide an overview of the most relevant findings on BAP1, underpinning its tissue specific tumour suppressor function." (PMID 36318367, 2022). "However, it remains unknown how BAP1 loss promotes tumor progression." (PMID 35954340, 2022).